CD4 (CD4 molecule)
Diseases named in the same sentence as CD4 in open-access papers (continued):
Sharing a sentence is not in itself a finding about the gene and the disease.
tumor (continued). "Moreover, it has been reported that CD4+ T cells recognize most tumor-specific immunogenic mutanomes, and that vaccination with such CD4+ immunogenic mutations confers antitumor activity and broadens CTL responses in mice." (PMID 29403496, 2018). "Anti-tumor effects were largely dependent on CD4+ T cells and partially dependent on CD8+ T cells." (PMID 30294332, 2018). "Across all studied mouse models, CTLA-4 expression appeared higher in the tumor and was largely restricted to CD4+FoxP3+ Treg cells (mean expression 68.3%), relative to CD4+FoxP3− effector (CD4+eff) T cells (10.2%, p < 0.0001) and CD8+ T cells (5.4%, p < 0.0001)." (PMID 29576375, 2018). "This may explain why neutrophil-derived ROS selectively impacted on CD27− γδ17 T-cell proliferation compared to CD27+ γδ T cells, CD8+ or CD4+ T cells in neutrophil-rich tumor models." (PMID 29750788, 2018). "In immunodeficient mice coinjected with KATO III and PBMCs, neutralization of CCL5 decreased tumor growth, suggesting that GC cells may induce CD4+ T cells to secrete the tumor-promoting CCL5 and may inhibit the anticancer activity of CD8+ cells." (PMID 29772686, 2018). "Furthermore, CD4+ T-lymphocytes from five of these pMMR tumours significantly increased their proliferative capacity when an α-PD-1 antibody was added to the coculture." (PMID 30285662, 2018). "Generation of anti-tumor Th1 responses within elderly tumors may be further compromised due to reduced CD4+ T cells and CD11b+CD8α−CD4+ cDCs whose main role is activation of Th1 responses." (PMID 30560130, 2018). "One could interpret it in a way that CD4 T cells that are close to CD8 T cells modulate their function which in turn influences CD8 engagement with proliferating tumor cells cf.." (PMID 30619761, 2018). "Moreover, MHC class II-blocking antibodies impaired the activation of tumor-specific CD4 T cells in the draining lymph nodes and inhibited migration to the tumor site and the activation of macrophages." (PMID 29032503, 2018). "It was proposed that tumor protection from CD4+ and CD8+ T cells is due to a large extent to the inhibition of antitumor T cells by hypoxia-driven local accumulation of extracellular ADO in the microenvironment, resulting from tumor metabolic adaptation to low oxygen tension." (PMID 29649100, 2018). "Biologically, both CD8 and CD4 T cells are expected to be highly discriminatory since co-localization of T cells and tumor cells reflects the presentation of tumor antigens, which is presumably higher in MSI cases, and the subsequent response of the immune system." (PMID 30619761, 2018). "TDEs from lymphocytic leukemia cells significantly decrease TGF-β1 expression of DC cells; in addition, DC cells pulsed with those tumor exosomes can more effectively stimulate CD4+ T cell proliferation in vitro and Th1 cytokine secretion and induced a tumor-specific CTL response." (PMID 30108680, 2018). "The expression of PD-1 on CD8+ and CD4+ T cells in tumor-DLNs were analyzed by flow cytometry." (PMID 29301578, 2018). "The anti-tumor functions of CD4 T-cell depend upon their specific subset (Th1, Th2, or Th17 cells)." (PMID 29765907, 2018). "First, they showed that CD4 T cells are crucial for tumor rejection." (PMID 29032503, 2018). "However we cannot assert that HELZ2V241M, IL-1βS230F and MLL2A4802S specific CD4+ T cell responses were sufficient to induce the elimination of the whole tumor cells observed during the complete response." (PMID 30459932, 2018). "Additionally, reduced CD25, CD73, and CTLA-4 on tumor-infiltrating CD4+ T cells in both age groups suggest reduced Treg-mediated suppression within IL-2/CD40-treated tumors." (PMID 30560130, 2018). "Interestingly, mIHC detected significantly higher Treg numbers than FACS and showed preferential CD4+ T cell distribution in the tumor stroma." (PMID 30042403, 2018). "In addition CD200fc-treatment also increased splenic CD4+ cells 12 days after injection of tumor cells." (PMID 29721190, 2018).
tumor (continued). "In 2008, a pilot clinical trial with anti-CTLA-4 (ipilimumab) treatment on 12 early UBC patients before radical cystectomy showed that the expression of inducible co-stimulator (ICOS) had increased significantly in CD4+ T-cell subpopulation from both tumor tissues and peripheral blood." (PMID 29358573, 2018). "Whether or not the integration of the OX40 costimulatory domain has an effect in the increase of CD4+ population, or whether the in vivo anti-tumor response is CD4+ dependent remain to be elucidated." (PMID 29975720, 2018). "Notably, cHL display a higher abundance of CD4+ TILs than DLBCL, consistent with literature, and further supporting the critical role of CD4+ T-cells in anti-tumor immunity in HL and as target for immunotherapy." (PMID 30384489, 2018). "Furthermore, we also found that the expression of STAT5 and TET2 were increased in CD4+ T cells from tumor tissues, and the massive STAT5 binds more TET2 to the FOXP3-TSDR and upregulates FOXP3 expression." (PMID 30013992, 2018). "Thus, tumor-induced CD4+ T cell anergy requires continuous Ag presentation in a tumor context and can be reversed by Ag restimulation in the absence of tumor." (PMID 29844317, 2018). "This discrepancy could be related to the presence in this latter model of 5–10% of CD25+ T cells in the transferred tumor-specific CD4+ T cells, probably corresponding to tTregs." (PMID 29844317, 2018). "Clinical evaluation of adoptive transfer or vaccination strategies should help interrogate the role of MHC class II restricted CD4+ T cells in human anti-tumor immunity, and could have clinical activity across multiple patients." (PMID 30400835, 2018). "Accordingly, tumor vaccine delivery after VGSC inhibition as a sequential “one-two punch” could activate new thymic CD4+ helper T-cells to restore lost immunological memory and sustain efficacious CTL antitumor responses." (PMID 30191140, 2018). "However, tumor-induced MDSCs downregulate expression of l-selectin on murine CD4+ and CD8+ naïve T cells and on blood-borne murine B cells in a contact-dependent manner that is independent of ADAM17." (PMID 29762501, 2018). "Moreover, loss of CD38 from CD4+ T cells increased intrinsic NAD+ levels and led to metabolic reprograming of T cells with superior anti-tumor properties." (PMID 30159123, 2018). "All the tissues examined showed lower percentages of CD4+ cells in tumor bearing mice." (PMID 29721156, 2018). "The quality of tumor immunity may ultimately depend upon the CD4+ subset transferred, and whether these subsets require CD8+ T cells to exert antitumor effects is unclear and will be discussed further below." (PMID 30140266, 2018). "Interestingly, not only CD8+ tumor-reactive T cells are isolated with this approach, but also effector CD4+ CTLs." (PMID 30233577, 2018). "7, tumor growth was also significantly inhibited by anti-CD4 mAb treatment." (PMID 29348598, 2018). "Furthermore, the combination of SEP and αPD-L1 induced significantly additive increase of CD3+, CD4+ or CD8+ T cells in tumor compared with SEP (each T cell P < 0.05, respectively, n = 6) or αPD-L1 (each T cell P < 0.05, respectively, n = 6)." (PMID 29317734, 2018). "Prophylactic or early therapeutic vaccination with GAds encoding nAgs in mice induced CD8+ and CD4+ T cells and efficiently controlled tumor growth, irrespective of the number of encoded nAgs." (PMID 30400835, 2018). "Histological and immunohistochemical analysis further revealed that in tumor-bearing mice treated with diosgenin and PD-1 mAb, the tumor necrosis, CD4+/CD8+ T-cell infiltration, and IFN-γ expression in tumor tissues were all upregulated more obviously than other cohorts." (PMID 30305604, 2018). "However, recent reports have indicated that the presence of CD4+ helper T lymphocytes, FoxP3+ Tregs and M2 cells can lead to favorable outcomes in certain tumor patients." (PMID 28977947, 2017).
tumor (continued). "CD4+CD25hiFoxP3+ T cell depletion resulted in increased proliferation and tumor-specific IFNγ secretion of the T cells, indicating that the CD4+CD25hiFoxP3+ T cells were capable of suppressing the expansion of tumor-reactive T cells." (PMID 28401257, 2017). "In a study in mice, the Sahin group found surprisingly that vaccinations using long peptides containing predicted CD8 T cell neoepitopes resulted in effective, tumor-directed T cell responses that were vastly dominated by neoepitope-specific CD4 T cell responses." (PMID 29312332, 2017). "In contrast, CD4+ T cells generally predominated in the stroma surrounding tumor cell nests." (PMID 28642820, 2017). "Similar results were observed when the HLA A2+ NY‐ESO‐1+ tumour cell line MEL624.38 was used as a target, confirming that CD4+ T cells could be reprogrammed to recognize tumour cells directly by producing Th1‐type cytokines." (PMID 27324616, 2017). "It has been reported that PD-1/PD-L1 interaction inhibits T lymphocyte proliferation, survival, and effector functions; promotes the differentiation of CD4+ T cells into Foxp3+ regulatory T (Treg) cells; and increases the resistance of tumor cells to cytotoxic T lymphocyte attacks." (PMID 28076847, 2017). "In this review the role of the EGFR for the functioning of the immune system is discussed, alongside how EGFR antagonist treatment could be impacting tumor growth by blocking macrophage and FoxP3-expressing regulatory CD4+ T cell function." (PMID 28970798, 2017). "In contrast, PD-1 levels increased in CD4+ T cells within both tumor and TdLN." (PMID 28839138, 2017). "Interestingly, these CD8+ Treg cells act synergistically with CD4+ Treg in the suppression of effecter T cells which further emphasized the importance of the understanding of the development and function of tumor-induced CD8+ Treg cells." (PMID 28487507, 2017). "Inter alia, a shift of CD4:CD8 ratio was observed that correlated with tumor progression." (PMID 28690586, 2017). "However, it is recognized increasingly that tumour‐specific CD4+ T cells also play an instrumental role in tumour control." (PMID 27324616, 2017). "As survival rates and tumor exclusion decreased in mice receiving immunized CD4+ and CD8+ cells, compared with those receiving immunized CD3+ cells, it was suggested that NKT cells, CD3+CD4−CD8−, might increase antitumor response induction by WEHI-NDV." (PMID 28864944, 2017). "By reducing the levels of Cbx3/HP1γ we can increase CD8+ effector T cells at the same time eliminate CD4+ Treg immune suppression in the tumor microenvironment that may control tumor growth." (PMID 28220815, 2017). "To further evaluate the systemic immunosuppressive status of the 2cKO tumor bearing mice, we calculated the population of CD4+ Foxp3+ Tregs in spleen, lymph nodes and peripheral blood from wild type mice or 2cKO tumor bearing mice respectively by quantitative flow cytometric analysis." (PMID 28592285, 2017). "Collectively, our findings indicate that CD4+CD26+ T cells could be used for TCR-based immunotherapy, as they may potentially mediate enhanced responses to mutated tumor antigen in an MHC II-restricted fashion." (PMID 29213079, 2017). "A more recent study shows that the chemotherapeutic drug cyclophosphamide induces the expression of CXCL3 by tumor cells, leading to intratumoral migration of CD4+ T cells expressing cytotoxic molecules, which are able to eradicate the tumor through specific tumor immunity." (PMID 29037250, 2017). "Indeed, pharmacological blockade of A2AR by antagonist repressed the tumor growth of 2cKO mice and reduced the population of CD4+ Foxp3+ Tregs." (PMID 28592285, 2017). "Our results, therefore, suggest that tumor-reactive effector CD4+ T cells are primed in LNs." (PMID 28290464, 2017). "TAA-specific CD8 and CD4 T cells play a pivotal role in anti-tumor immunity." (PMID 28477011, 2017).
tumor (continued). "However, more tumor reduction in the mice treated with an Akti-inhibited mixture of CD4 + CD19CAR and CD8 + CD19 CAR T cells indicates the minor impact of Akti-treated Tregs on the overall therapeutic effects." (PMID 28331616, 2017). "For this purpose, we plotted the frequencies of 35 most frequent TCRs expressed by CD4+Teffs and Tregs isolated from lymph nodes or infiltrating the B16-Ep63K tumor, against their frequencies in the total repertoire of healthy, non-tumor-bearing TCRmini mice (untreated)." (PMID 28638937, 2017). "In the tumor microenvironment (TME), Treg cells might decrease the proliferation of CD4+ T lymphocytes by cell contact inhibition, which would reduce the local immune response to tumors such that the tumor cells could escape immune surveillance." (PMID 28796055, 2017). "It is also possible that tumour‐specific CD4+ T cells may promote epitope spreading by neutralizing the immunosuppressive effects of the tumour microenvironment." (PMID 27324616, 2017). "Consequently, it is assumed that the tumor's growth is limited and the production of CD4+ T cells and the antitumor cytokine due to tumor cells is also limited." (PMID 29250133, 2017). "Moreover, both tumor growth and spontaneous distant organ metastasis of 4T1LN from the CD4+ T cell‐depleted mice or CD25+ cell‐depleted mice were significantly reduced." (PMID 28993429, 2017). "Our in vivo CD4 imaging in the presence of ATA is consistent with tumor studies in patients which showed that these immune complexes are cleared rapidly by the liver resulting in high hepatic uptake, altered blood clearance, and reduced target uptake of the radiotracer." (PMID 29121114, 2017). "On the other hand, multiple studies in alcohol-consuming mice showed an increase in the percentage of cells known to suppress anti-tumor T cell immune responses, such as T regulatory cells (Tregs) (CD4+CD25+FOXP3+) and invariant natural killer T cells (iNKT) cells (CD3+NK1.1+)." (PMID 28805741, 2017). "In a Th1 microenvironment, proinflammatory cytokines (e.g., IL-6 and IL-1) may contribute to tumour eradication by attracting leucocytes from the circulation and by increasing CD4 + T cell activity." (PMID 29089667, 2017). "Moreover, DC-based HHP vaccine generated from NSCLC patients induced tumor antigen-specific CD4+ and CD8+ T cell responses in vitro." (PMID 28187172, 2017). "Furthermore, pharmacological blockade of A2AR in vivo by antagonist SCH58261 repressed the tumor growth, inducing a reduction of CD4+ Foxp3+ Tregs and an enhanced anti-tumor response of CD8+ T cells." (PMID 28592285, 2017). "However, the observation that depletion of CD4+ T cells at the start of the MLTC enhanced the generation of tumor-specific CD8+ T cells indicates that prevention of CD4+CD25hiFoxP3+ T cell accumulation is beneficial for an efficient MLTC." (PMID 28401257, 2017). "We separately stained lung sections for Twist expression to determine whether the combination therapy also led to greater co-localization of CD4+ T-cells with micro- and macro-metastatic deposits of 4T1 tumor cells." (PMID 29207606, 2017). "Here we have demonstrated that for obinutuzumab, when given in combination with a systemic TLR7 agonist, long-term tumor-free survival appears to be dependent on NK cells and CD4+ T cells with macrophages and monocytes only able to mediate short-term increases in survival." (PMID 27890931, 2017). "Furthermore, over expression of TLR4 on hepatocellular carcinoma cells was positively correlated with the number of CD4+CD25highFOXP3+ Treg in tumor tissue, which leads to immune tolerance and tumor progression." (PMID 29029545, 2017). "Similarly, it has been shown that compared with combination with anti-TGF or anti-IL-10R, combination with anti-CTLA-4 strikingly improves the therapeutic effect of VSV-mediated tumor regression by eliciting CD4+ and CD8+ T cells response." (PMID 28567163, 2017).
tumor (continued). "Indeed, the best characterized immune cells in cancer biology are CD4+ helper T-cells, which exacerbate tumor proliferation, and cytotoxic CD8+ T-cells, which have been shown to prevent tumor growth." (PMID 29285416, 2017). "Enhanced 4T1 tumor targeting was visualized by IHC analysis of lung tissue sections, whereby regions of metastasis, characterized by elevated Twist expression, had significantly greater levels of CD4+ T-cell infiltrate after the combination treatment." (PMID 29207606, 2017). "It has long been known that exogenous TGFβ has the ability to induce Treg differentiation from naïve CD4 T cells, and it has been suggested in a number of murine studies that this mechanism might be important during tumour-mediated Treg induction." (PMID 28239749, 2017). "In CAR T-cell therapy, this feedback loop may provide a means of replicating the “inflamed” immunophenotype of tumours enriched in IFNγ due to DC-mediated antigen presentation to CD4+ and CD8+ T-cells." (PMID 29157300, 2017). "However, IFN-γ and other cytokines produced by CD4+ Th1 T-cell can also target tumor cells directly thereby keeping tumors in check, possibly by inducing p27 as discussed here." (PMID 28665315, 2017). "Upon phagocytosis of dying cancer cells, DCs fulfil their primary role by processing and presenting tumor Ags to CD4+ T helper cells, while some subsets of DCs possess the capability to cross-present tumor Ags to CD8+ T cells, and thus stimulate the effector cells of the antitumor response." (PMID 28439087, 2017). "The proportion of CD4+CD25+FOXP3+ Treg cells was significantly higher in the different HCC tumor stage groups than in the control group; moreover, the proportion of CD4+CD25+FOXP3+ Treg cells was significantly higher in the advanced (stage III-IV) HCC group than in the early (stage I–II) HCC group." (PMID 28796055, 2017). "Since these subsets represent a minority of the tumour-infiltrating CD4+FoxP3− cells, their exact role in the anti-tumour response is unclear, though they may serve to enhance the proliferation and activation of the tumour-infiltrating cytotoxic T cells." (PMID 28194010, 2017). "Whereas mice that had rejected the original tumor in the absence of NK cells rejected the tumor rechallenge, mice which had been depleted of CD4 or CD8 T cells during the primary therapy were significantly more likely to succumb to tumor upon rechallenge (P=0.018, P=0.004, respectively)." (PMID 27890931, 2017). "This implies that our findings on radiotherapy-induced increased PD-1 expression on CD4+ T cells may underestimate the effect of radiotherapy on the tumor and its microenvironment." (PMID 28344877, 2017). "We speculate that both the reduction of tumor infiltrating regulatory CD4 T cells and costimulation of effector T cells by aGITR contributed the enhancement of active immunization with aCD122 therapy; additional studies will be required to address this." (PMID 29312597, 2017). "There appeared to be a concomitant increase in the absolute Tfh numbers in these tumours (defined by CD4+FoxP3-CXCR5+PD-1+ICOS+ lineage), although the relative percentage of these cells remained low and not substantially different from the other treatment groups." (PMID 28194010, 2017). "Notably, most tumor-infiltrating Tregs and CD4+Teffs displayed activated (CD62Llow) phenotype irrespectively of the DTA-1 treatment and elevated GITR expression, suggesting that TCRs of these cells have been triggered." (PMID 28638937, 2017). "More recently, infiltrating CD4+T cells could promote tumor metastasis by enhancing cancer cell invasion via modulation of FGF11/miRNA-541/AR/MMP9 signaling." (PMID 29197379, 2017). "Importantly, long-term surviving animals, which had been cured by combined anti-CD4/anti-PD-1 mAb immunotherapy, showed persistent immunity towards Luciferase-expressing, as well as parental-unmodified-tumor cells." (PMID 29070883, 2017).